CDK4 (cyclin dependent kinase 4)
Diseases named in the same sentence as CDK4 in open-access papers (continued):
Sharing a sentence is not in itself a finding about the gene and the disease.
melanoma (continued). "For melanomas, regulators of the cell cycle’s G1 phase transition such as D and E type cyclins, CDK4/6, CDK inhibitors including p16 and p14, and retinoblastoma protein were suggested as diagnostic tools or therapeutic targets." (PMID 32977329, 2020). "Performing germline/tumour whole-exome sequencing of 44 stage III/IV melanoma patients we identified pathogenic germline mutations in CDKN2A, CDK4, ATM, POLH, MRE11A, RECQL4 and XPC, affecting 7/44 patients." (PMID 33077847, 2020). "Immunofluorescence staining confirmed inhibition of cyclin D1 and CDK4 in melanoma A375 cells exposed to L-KYN." (PMID 33114713, 2020). "Previous studies demonstrate that CDK4/6 inhibitors reduced melanoma cell growth and synergized with BRAF and MEK inhibitors." (PMID 32413516, 2020). "We apply this platform to profile immunopeptidomic changes in melanoma cell lines, comparing treatment with palbociclib (a small-molecule CDK4/6 inhibitor) and interferon-γ (IFN-γ), both known modulators of antigen presentation." (PMID 32488085, 2020). "Teh’s study demonstrated that CDK4/6 inhibitors in combination with BRAF inhibitors or MEK inhibitors are an effective treatment strategy for melanoma, but continued administration increases toxicity." (PMID 32357912, 2020). "Single-arm studies evidenced clinical activity of CDK4/6 inhibitors in a subset of patients suffering from mantle cell lymphoma, liposarcoma, melanoma, non-small cell lung cancer, glioblastoma, neuroblastoma and malignant rhabdoid tumors." (PMID 33255177, 2020). "In 2015, a revision of the prevalence of mutations in susceptibility CMM genes reported that, in 2511 melanoma-prone pedigrees, the mutation prevalence was about 20% for CDKN2A, 0.7% for CDK4, 1% for BAP1, and 0.5% for POT1." (PMID 33322357, 2020). "In recent work, the combination of CDK4 and MDM2 inhibitors demonstrated significant preclinical activity, and this combination was effective in melanoma models with genetic loss of CDKN2A." (PMID 33076392, 2020). "Recent studies have led to the identification of new genes involved in CMM susceptibility: beyond CDKN2A and CDK4, BAP1, POT1, and MITF were recently identified as potential high-risk melanoma susceptibility genes." (PMID 33322357, 2020). "Familial history is also one of the risk factors for developing melanoma, with cyclin-dependent kinase inhibitor 2A (CDKN2A) and cyclin-dependent kinase 4 (CDK4) being the most common heritable mutations." (PMID 32092958, 2020). "CDK4: Given the probability of developing multiple melanoma equivalent to about 40%, we suggest to carry on clinical and instrumental skin re-evaluation with a 3-month follow-up frequency." (PMID 33322357, 2020). "Cyclin D1 overexpression is sufficient to increase melanoma BRAFi resistance but this phenomenon is even more enhanced when cyclin D1 and CDK4 are concurrently overexpressed." (PMID 32605090, 2020). "We applied our quantitative multiplexed hipMHC normalization to determine the pMHC repertoire response to CDK4/6 inhibition with palbociclib treatment in melanoma." (PMID 32488085, 2020). "Overexpression of let-7b in melanoma cells also reduced the expression of the cell cycle promoters cyclin D1, cyclin D3, cyclin A and cyclin-dependent kinase 4 (CDK4)." (PMID 31906510, 2020). "Preclinical evidence of effectiveness of CDK4/6 inhibition also exists in other malignancies, such as myeloma and melanoma." (PMID 32792963, 2020). "The molecular mechanism of cell cycle arrest also involves the downregulation of cyclin D1 and CDK4 complex in B cell malignancies, bladder cancer, melanoma, and HepG2 hepatocarcinoma cell lines." (PMID 33291743, 2020). "Patnaik and Taylor’s study showed that CDK4/6 inhibitors achieved disease control rates of 49% and 44%, respectively, in non-small-cell lung cancer patients (n = 68) and melanoma patients (n = 18)." (PMID 32357912, 2020).
melanoma (continued). "Oncogenomic studies indicate that somatic CNV of some genes is involved in melanoma progressions, such as mutated gene amplifications in CCND1, CDK4, and TERT, of which the CNV status also has been reported in Chinese melanomas." (PMID 32083130, 2020). "This transporter was found to drive mTORC1 signaling and contribute to cyclin dependent kinase 4/6 (CDK4/6) inhibitor resistance in melanoma." (PMID 32854217, 2020). "Melanoma-associated CDKN2A missense mutations commonly diminish the capacity of p16INK4a to bind and inhibit CDK4/6." (PMID 33076392, 2020). "p16-cyclinD-CDK4/6-retinoblastoma protein pathway, also known as CDK4 pathway, is dysregulated in 90% of melanomas." (PMID 32850962, 2020). "Palbociclib has antitumor activity for NRAS-mutant melanomas in a preclinical mouse model, indicating the CDK4 pathway as a potential therapeutic target." (PMID 31358010, 2019). "Prompted by pronounced effects of the CDK4/6 inhibitor palbociclib in melanoma xenograft studies we used specific si/sh- RNA to delete either CDK4 or CDK6 in human melanoma cell lines." (PMID 30858922, 2019). "Effects upon CDK6 knockdown seem to be even stronger compared to CDK4 which extended to the migratory behaviour of melanoma cells in a wound healing assay." (PMID 30858922, 2019). "The rationale for combining these drugs is that several proteins, which are linked to melanoma cell response and resistance to BRAFV600/MEK-targeting agents, are HSP90 clients including ARAF, CRAF, BRAFV600E, CDK4, COT, IGF1R, PDGFR-β and AKT." (PMID 30989459, 2019). "Patient-derived xenograft models (PDX) were performed to detect the effects of CDK4/6 inhibitors on the proliferation of mucosal melanoma cells with altered copy number of CDK4 pathway (CDK4, Cyclin D1 and P16INK4a)." (PMID 31358010, 2019). "Although high-level p16 expression normally halts cellular proliferation by inhibiting the ability of cyclin D/CDK4/6 complexes to phosphorylate and inactivate pRb, human melanomas and DLBCLs can escape the effect of p16 by inducing cyclin E expression." (PMID 30125329, 2018). "A cross-sectional study was conducted by genotyping CDKN2A/CDK4 variants and selected MC1R polymorphisms in 52 melanoma-prone families." (PMID 29774366, 2018). "Since disruption of the CDK4/Rb pathway is frequent in many melanomas the cyclin D1-CDK4/6-Rb axis is considered a major driver of melanomagenesis." (PMID 29541385, 2018). "hMELTs are immortalized with both hTERT and CDK4R24C, and prior studies establish the ability of constitutive CDK4/Cyclin D1 activity to drive MAPK-independent melanoma growth." (PMID 29875996, 2018). "In the present study, we investigated 18F–FDG-PET/CT and DW-MRI for the in vivo monitoring of a novel BRAF and CDK4/6 inhibitor combination therapy in human melanoma xenografts in mice." (PMID 29347968, 2018). "Since the CDKN2A–CDK4/CDK6–cyclin D axis is often disrupted in melanoma CDK4/CDK6 inhibitors (e.g., abemaciclib and palbociclib) are predicted to be effective in the treatment of melanoma." (PMID 29946532, 2018). "Familial melanoma is responsible for 8–12% of melanoma cases, being cyclin-dependent kinase inhibitor 2A (CDKN2A) and CDK4 the major susceptibility genes involved in this context." (PMID 30166456, 2018). "In melanoma-dominant or melanoma-subordinate pedigrees or in individuals carrying a BAP1, CDK4, CDKN2A, MITF, or POT1 mutation, individuals should be educated on the importance of melanoma prevention and early detection." (PMID 28283772, 2017). "After the identification of CDKN2A and CDK4 genetic testing of families with hereditary malignant melanoma is possible." (PMID 27804060, 2017).
melanoma (continued). "After 72 h of exposure, CDK4 inhibitor palbociclib reduced melanoma cell proliferation of Ma-Mel-123 cells with significantly higher efficiency than BRAF inhibitor vemurafenib (p = 0.0017)." (PMID 27903987, 2017). "Fascaplysin, as a natural compound isolated from marine sponge, exhibits anti-cancer effects in multiple types of cancer cell, including small cell lung cancer, melanoma, and glioma through suppression of CDK4-mediated cell cycle progression." (PMID 29295560, 2017). "Although CDK4/6 inhibitors can reduce melanoma cells growth both in vitro and in animal models, the effects of these drugs appear to be mainly cytostatic." (PMID 29371923, 2017). "In both studied melanoma cell lines expression of cyclins D1 and D3, cyclin-dependent kinases CDK4 and CDK6 were observed." (PMID 29214525, 2017). "In vitro, G1T38 decreased RB1 (RB) phosphorylation, caused a precise G1 arrest, and inhibited cell proliferation in a variety of CDK4/6-dependent tumorigenic cell lines including breast, melanoma, leukemia, and lymphoma cells." (PMID 28418845, 2017). "CDK4/6 inhibitors represent promising candidates for cancer therapy, since alterations in the cyclin D-CDK4/6-p16INK4A-Rb pathway occur frequently in various type of tumors, including the majority of melanomas, and promote continued growth." (PMID 29371923, 2017). "p-AKT levels were significantly reduced in melanoma cells expressing hSulf-1, and cytoplasmic CDK4 levels increased while nuclear CDK4 levels decreased." (PMID 27806323, 2016). "CoQ0 treatment (0-20 μM) for 24 h caused a dose-dependent reduction of cyclin E and its up-stream kinase, CDK4 in B16F10 melanoma cells." (PMID 26968952, 2016). "In an inducible NRAS Q61K genetically engineered mouse model of melanoma, the combination of MEK and CDK4/6 inhibitors caused tumor regression that paralleled extinction of mutant NRAS, but either monotherapy alone did not." (PMID 27167191, 2016). "Knocking down AKT in the parental M21 and A375 melanoma cells also appeared to inhibit CDK4 nuclear import, suggesting that the hSulf-1-induced changes in CDK4 subcellular localization are related to AKT." (PMID 27806323, 2016). "Taken together, these data suggest that CoQ0 treatment also promotes cell growth inhibition by inducing G1/S transition phase arrest, followed by the down-regulation of cyclin D1/E and CDK4 expression in melanoma cells." (PMID 26968952, 2016). "We further confirmed that hSulf-1 overexpression can inhibit AKT phosphorylation and CDK4 nuclear localization and retard the growth of melanoma xenograft tumors in nude mice." (PMID 27806323, 2016). "Further study revealed that the hSulf-1-induced changes in the biological behaviors of melanoma cells are closely associated with reduced AKT phosphorylation and reduced CDK4 nuclear import." (PMID 27806323, 2016). "We found that with hSulf-1 expression, AKT phosphorylation in melanoma cells was significantly reduced, as were nuclear CDK4 levels." (PMID 27806323, 2016). "Sensitivity to PD0332991, a therapeutic CDK4/6 inhibitor was also evaluated in the melanoma cell lines." (PMID 26201960, 2015). "Specifically, the CDK4/6 inhibitor PD-0332991(Palbociclib) has demonstrated anti-tumor activity in melanoma." (PMID 25537510, 2015). "have demonstrated that CDK4/6-dependent activation of the FOXM1 transcription factor suppressed senescence by an activation of critical G1/S genes promoting S phase entry in melanoma cells." (PMID 25684390, 2015). "CDK4/Cyclin D kinase constitutes an established pharmacological target in several human cancers, in particular in melanoma and in KRAS-mutant NSLCL lung cancers." (PMID 25625291, 2015). "Amplification of cyclin D, which binds to CDK4, can drive cell cycle progression, and has been observed in a subset of melanomas." (PMID 26201960, 2015).
melanoma (continued). "Two ongoing phase I/II clinical trials are proceeding in NRAS-mutant melanoma combining MEK inhibitors with CDK4/6 inhibitors with promising early results: 1) binimetinib and LEE011 and 2) trametinib and palbociclib." (PMID 25537510, 2015). "The p16INK4a-cyclin D-CDK4/6-retinoblastoma protein pathway (CDK4 pathway) is dysregulated in 90% of melanomas." (PMID 25625291, 2015). "As fascaplysin, a laboratory grade CDK4 inhibitor, showed significant activity in the melanoma cell lines, we tested a therapeutic CDK4/6 inhibitor PD0332991 in the panel of melanoma cell lines." (PMID 26201960, 2015). "Further testing of the therapeutic CDK4 inhibitor PD0332991 showed that 4 out of 8 melanoma cell lines tested are sensitive to CDK4 inhibition and that CDK4 inhibition induces apoptosis in melanoma cells." (PMID 26201960, 2015). "Early clinical results are supportive of a potential increased antitumor effect achieved by combining a MEK inhibitor with a CDK4/6 inhibitor in patients with NRAS mutant melanoma." (PMID 25645078, 2015). "CDK4 hyperactivity has been well documented in a wide variety of cancers, and in particular in melanoma, lung cancer and lymphoma." (PMID 25625291, 2015). "We performed genetic analysis of CDKN2A, CDK4, BAP1, MC1R, and MITFp.E318K in Danish high-risk melanoma cases and found CDKN2A germline mutations in 11.3% of CM families with three or more affected individuals, including four previously undescribed mutations." (PMID 25803691, 2015). "The G1 phase arrest in the melanoma cells after their treatment with anti-miR-106b was associated with marked suppression of the expression of both cyclins and CDKs (CDK2, CDK4 and CDK6) and concomitant reactivation of p21/WAF1/Cip1 protein." (PMID 25361006, 2014). "Suppression of miR-106b in A375 and Hs294t human melanoma cells caused inhibition of cyclin D1, D2 and E, and reduction in the expression levels of CDK2, CDK4 and CDK6 proteins in both cell lines." (PMID 25361006, 2014). "A recent study of miR-206 in melanoma showed that it targeted CDK4, Cyclin C and Cyclin D1 which were cell cycle genes." (PMID 25255814, 2014). "Significantly, CDK4 pathway is deregulated in most melanomas as a consequence of increased activity of ERK or deletion of CDK4 inhibitor p16INK4A (below)." (PMID 24743024, 2014). "In 2012 an inducible mouse model of NRAS mutant melanoma and network modelling established the in-vivo therapeutic syngeristic efficacy of targeted inhibition of CDK4 and MEK to decrease melanoma survival and proliferation." (PMID 24216705, 2013). "Minor familial melanoma loci have been more commonly found in the general population with a lower penetrance of their germline mutation than CDKN2A and CDK4." (PMID 24416617, 2013). "Identified high-penetrance variants for melanoma risk include cyclin-dependent kinase inhibitor 2A (CDKN2A), cyclin-dependent kinase 4 (CDK4), an alternate reading frame (ARF) of CDKN2A, and a locus on 1p22." (PMID 24392023, 2013). "Various genetically modified mouse models are used in melanoma research to study melanomas generation and progression (e.g. Hgf-Cdk4(R24C) mice) or as a model for subcutaneous tumor nodule formation." (PMID 23342051, 2013). "Our analyses pointed out a down modulation of cell cycle regulators cyclin B1, cdc25B, and CDK4, which certainly contributes to the inhibition of cell proliferation exerted by D6 on melanoma cells." (PMID 23642048, 2013).
melanoma (continued). "Homo sapiens cyclin-dependent kinase inhibitor 2A (CDKN2A; melanoma, p16, inhibits CDK4), a major CDK inhibitor, is the product of a tumor-suppressor gene that has been found inactivated in different cancer types." (PMID 22690114, 2012). "Increase of CYCLIN D1 and CDK4 proteins in melanoma cells can also be a consequence of gene amplification." (PMID 21860617, 2012). "Two high-penetrance susceptibility genes, CDKN2A and CDK4 and one low-penetrance gene, MC1R, are well-defined genetic risk factors for melanoma." (PMID 22978401, 2012). "Among the 5-10% of melanomas with strong familial linkage or inherited germline defects, mutations in p16 (CDKN2A) and CDK4 are common findings, as is loss of p27 and p16 expression during progression of sporadic melanomas." (PMID 19949544, 2009). "Two high penetrance melanoma susceptibility genes, CDKN2A and CDK4, and a low penetrance gene, MC1R, have been identified." (PMID 18803811, 2008). "Homozygous deletion (log2 ratio < -1) of the region containing the tumor suppressor gene cyclin-dependent kinase inhibitor 2A (melanoma, p16, inhibits CDK4) (CDKN2A) was observed in two samples, and heterozygous deletion in one sample." (PMID 18522746, 2008). "We analysed 15 Italian melanoma families for germ line mutations in the coding region of the CDKN2A gene and exon 2 of the CDK4 gene." (PMID 11556834, 2001). "This study suggested that combined MEK inhibitor with CDK4/6 inhibitor may be clinically more active in NRASmut melanoma patients with concurrent genetic alterations (such as CDKN2A, CDK4, or CCND1) in G1 cell‐cycle checkpoint than MEK inhibition alone." (PMID 41492362, 2026). "In melanoma, inhibition of PRMT5 sensitizes melanoma cells to CDK4/6 inhibitor." (PMID 41513606, 2026). "First, there was a preclinical study in melanoma demonstrating that the combination of CDK4/6 plus MEK inhibitors has greater efficacy in immunocompetent models relative to immunodeficient models, and that CD8 + T cells contribute to the antitumor effects of this combination." (PMID 41428766, 2025). "Notably, CDK4/6 pathway alterations are found in up to 90% of human melanomas, and CDK4 copy number changes have been reported in canine melanoma." (PMID 40642276, 2025). "Among melanoma‐prone families, wild‐type for CDKN2A and CDK4, some have pathogenic variants in genes not usually linked to melanoma." (PMID 40072281, 2025). "CDK4 activation inhibits the retinoblastoma protein, promoting cell cycle progression, and is usually associated with tumor suppressor CDKN2A (p16INK4A) deletion, furthering melanoma cell survival." (PMID 40076927, 2025). "The CDK4/6 pathway is frequently dysregulated in melanoma, particularly in tumors with intact retinoblastoma (RB) protein, which comprise the large majority of melanomas." (PMID 40282469, 2025). "For example, analyzing pathways linking disease CMM1 to known melanoma-associated genes CDKN2D and CDK4, with edge thickness representing attention weights, revealed a key pathway (CMM1 → MC1R → Mole → CDK4/CDKN2D) offering novel insights into melanoma pathogenesis." (PMID 40680165, 2025). "Together, these papers suggest that strategies to decrease CDK6 levels in melanoma may improve response to CDK4/6is." (PMID 40282469, 2025). "The clinical phenotype observed in families with CDK4 variants is similar to that of families with CDKN2A variants, exhibiting a significant presence of dysplastic nevi, along with an elevated risk of developing multiple primary melanomas." (PMID 40558591, 2025). "Here, we provide an update on developments that may lead to more effective CDK4/6i combination therapies targeting the cell cycle for the second- or third-line treatment of melanoma." (PMID 40282469, 2025).